ATG16L1 (autophagy related 16 like 1)
Diseases named in the same sentence as ATG16L1 in open-access papers (continued):
Sharing a sentence is not in itself a finding about the gene and the disease.
fungal keratitis (1 paper, 2025). "In the context of fungal keratitis, miR-223 targets the autophagy-related gene ATG16L1, dampening the autophagic activity of corneal stromal cells and murine corneal tissues, exacerbating keratitis, thereby elevating IL-1β levels within the tissue." (PMID 40989245, 2025).
gastric adenocarcinoma (1 paper, 2024). "The ATG16L1 is a key gene involved in autophagosome formation and modulating inflammation, which can lead to gastric adenocarcinoma." (PMID 38353395, 2024).
gastritis (1 paper, 2023). Inflammation of the stomach. "The present study shows that ATG16L1 and ATG12 are susceptibility genes of H. pylori-infected gastritis." (PMID 37629426, 2023).
HIV-1 infection (1 paper, 2024). The type species of lentivirus and the etiologic agent of acquired immunodeficiency syndrome (AIDS). "Notably, we have previously shown that autophagy suppresses mucosal HIV-1 infection and transmission at the early steps of the virus replication cycle via an ATG16L1-TRIM5α-mediated mechanism." (PMID 38548722, 2024). "Our findings highlight host autophagy, and in particular ATG16L1, as an emerging target for HIV-1 therapies, underscoring the relevancy of repurposing clinically-approved autophagy drugs to restore immune function in chronic HIV-1 infection." (PMID 38548722, 2024).
Hyperbilirubinemia (1 paper, 2014). An increased amount of bilirubin in the blood. "Genetic analysis of the frequency of minor allele of NOD2, CARD9, RAC1 and ATG16L1 polymorphisms in IF patients with conjugated hyperbilirubinemia (CB≥100 μmol/L)." (PMID 24465786, 2014). "Genetic analysis of the frequency of minor allele of NOD2, CARD9, RAC1 and ATG16L1 polymorphisms in IF patients with conjugated hyperbilirubinemia (CB≥50 μmol/L)." (PMID 24465786, 2014).
Hyperinsulinemia (1 paper, 2018). An increased concentration of insulin in the blood. "Next, we found that the expression of major components of the autophagy process, including Beclin-1, Atg7, Atg3, Atg12-Atg5, free Atg12, Atg16L1, and LC3II was not affected by hyperinsulinemia." (PMID 29719598, 2018).
intestinal infection (1 paper, 2020). "In addition, Atg16L1-hypomorphic mice developed intestinal abnormalities resembling CD whilst displaying resistance to intestinal infection with the bacterium Citrobacter rodentium." (PMID 32313116, 2020).
intestinal tumors (1 paper, 2025). "Furthermore, we examined whether the functioning interplay between ATG16L1 and XBP1, which is known to contribute to sporadic Crohn-like enteritis in mouse models of IBD, might be involved in transcription-associated mutagenesis and the manifestation of intestinal tumors." (PMID 41057521, 2025). "However, in contrast to the loss of proliferative arrest, we surprisingly found that aged Atg16l1/Rnaseh2bΔIEC mice did not develop spontaneous intestinal tumors." (PMID 41057521, 2025).
Kawasaki disease (1 paper, 2023). A rare inflammatory disease characterized by an acute febrile, systemic, self-limiting, medium-vessel vasculitis primarily affecting children. "It has been documented that in the leukocytes of CAL-injured children with Kawasaki disease, the expression of ATG16L1 continues to decrease even after treatment, suggesting that ATG16L1 may be involved in the process of CAL." (PMID 38114939, 2023). "The autophagy markers ATG16L1, BECN1, and LC3II are downregulated in the expression of IVIG-resistant Kawasaki disease." (PMID 38114939, 2023). "BECN1 was positively correlated with ATG16L1, while the incidence of IVIG-resistant Kawasaki disease, CAL, AST, NK% were negatively correlated with it (p < 0.05)." (PMID 38114939, 2023). "RBC, HB, CK, CK-MB, ALB, A/G, LC3II, ATG16L1 were positively correlated with BECN1; the incidence of IVIG-resistant Kawasaki disease, length of stay, lymph node enlargement, perianal desquamation, CAL, IL-4, IL-6, CRP, PCT, SF, CD3 + CD4 + T, and r-GT were negatively correlated with BECN1." (PMID 38114939, 2023). "ATG16L1 0.42 (0.34, 0.50) vs. 0.49 (0.41,0.61), BECN1 0.46 (0.41, 0.63) vs. 0.83 (0.66,1), LC3II 0.41 ± 0.21 vs. 0.71 ± 0.19 were significantly downregulated in the IVIG-resistant Kawasaki disease group(P < 0.05), and LAMP2, p62 were not significantly different." (PMID 38114939, 2023).
latent infection (1 paper, 2016). "Collectively, our data reveal that miR-20a is induced by mycobacterial infection, and suppresses the protein expression of ATG7 and ATG16L1, thereby inhibiting autophagic response and promoting latent infection of M. tuberculosis and survival in macrophages." (PMID 27803889, 2016). "In this study, we found that miR-20a plays a novel role in inhibiting autophagy and promoting mycobacterial latent infection in macrophages by targeting ATG7 and ATG16L1, which may provide a better understanding of M. tuberculosis latent infection." (PMID 27803889, 2016).
leukemia (1 paper, 2013). A malignant (clonal) hematologic disorder, involving hematopoietic stem cells and characterized by the presence of primitive or atypical myeloid or lymphoid cells in the bone marrow and the blood. "Accordingly, ATG16L1 was down-regulated in GC-resistant patients, which might lead us to speculate that induction of autophagy might help to overcome GC-resistance in IBD patients, as it happens in leukemia." (PMID 24155895, 2013).
liver cancer (1 paper, 2023). An epithelial or non-epithelial malignant neoplasm that arises from the liver. "For example, in liver cancer, circMDK upregulates ATG16L1 by inhibiting miR-346 and miR-874-3p, which promotes the occurrence and development of liver cancer." (PMID 37781524, 2023).
liver disease (1 paper, 2022). "To address whether autophagy inhibition and NEMO deletion act synergistically in the development of spontaneous liver disease, we generated mice lacking both ATG16L1 and NEMO in LPCs (ATG16L1LPC-KO NEMOLPC-KO) and compared them to the respective single knockouts." (PMID 35626041, 2022).
lung adenocarcinoma (1 paper, 2017). A carcinoma that arises from the lung and is characterized by the presence of malignant glandular epithelial cells. "ATG10 rs10036653, ATG12 rs26538, ATG16L1 rs2241880 and ATG16L2 rs11235604 were significantly associated with OS of gefitinib-treated advanced lung adenocarcinoma patients (all P < 0.05)." (PMID 29259263, 2017). "We found that ATG10 rs10036653, ATG12 rs26538, ATG16L1 rs2241880 and ATG16L2 rs11235604 were significantly associated with survival of lung adenocarcinoma patients (all P < 0.05)." (PMID 29259263, 2017).
lupus nephritis (1 paper, 2023). Glomerulonephritis in the context of systemic lupus erythematosus. "Therefore, we suggest that Atg16L1 might serve as a therapeutic target for the treatment of altered phagocytosis-related diseases such as bacterial infection, inflammation, lupus nephritis, and cancer." (PMID 36451006, 2023).
lymphopenia (1 paper, 2017). Reduction in the number of lymphocytes. "The lymphopenia upon specific deletion of Atg3, Atg5, Atg7, Atg16l1, or Vps34 in T cells has been demonstrated to be associated with increased percentages of activation/memory-like T cells within both the CD4+ and CD8+ compartments." (PMID 28572806, 2017). "Enhanced T cell activation/memory in the absence of Atg3, Atg5, Atg7, Atg16l1, or Vps34 can be partially attributed to peripheral T cell lymphopenia." (PMID 28572806, 2017).
malnutrition (1 paper, 2021). Inadequate nutrition resulting from poor diet, malabsorption, or abnormal nutrient distribution. "ATG3, ATG5, ATG7, or ATG16L1 deficiency in mice leads to malnutrition and energy expenditure, leading to death shortly after birth." (PMID 33854691, 2021).
mastitis (1 paper, 2022). Inflammation of breast tissue during lactation or postpartum due to an obstructed duct or infection. "Our results reveal that Z. morio hemolymph alleviates E. coli-induced mastitis via lessening the inflammatory response by regulating the NLRP3 and ATG5/ATG16L1 signaling pathway, as well as repairing the blood-milk barrier." (PMID 36362066, 2022).
memory impairment (1 paper, 2023). "Recent results showed that aged mice lacking this C-terminal domain of Atg16L1 develop beta amyloid plaques, excessive tau phosphorylation, reactive microgliosis, and memory impairments." (PMID 36901549, 2023).
metastatic melanoma (1 paper, 2021). A melanoma that has spread from its primary site to another anatomic site. "On the other hand, we did not observe any differences in the expression of ATG16L1 between benign nevi, primary and metastatic melanoma specimens." (PMID 34458153, 2021).
necrotizing enterocolitis (1 paper, 2014). Necrotizing enterocolitis (NEC) is a devastating disease that affects mostly the intestine of premature infants. "Lastly, we examined whether there were any differences in the frequency of the polymorphisms of NOD2, CARD9, RAC1 and ATG16L1 in relation to inflammatory etiologies of IF such as in the cases with necrotizing enterocolitis (NEC)." (PMID 24465786, 2014).
oral cavity cancer (1 paper, 2017). A primary or metastatic malignant neoplasm involving the oral cavity. "ATG16L1 rs2241880 was unequally distributed in oral cavity cancer." (PMID 28761177, 2017).
oral cavity squamous cell carcinoma (1 paper, 2017). A squamous cell carcinoma arising from the oral cavity. "Finally, we found an association in the distribution of CC genotypes in the dominant and recessive models of ATG16L1 rs2241880 polymorphism and a higher risk to suffer from oral cavity squamous cell carcinoma." (PMID 28761177, 2017).
pericarditis (1 paper, 2014). An inflammatory process affecting the pericardium. "Nonetheless, it is interesting to note that rs2241880 in ATG16L1 resulted associated with a minor risk to develop pericarditis as a complication." (PMID 25369137, 2014). "For example, PTPN2 SNP resulted associated with a higher risk to develop pericarditis and serositis, while ATG16L1 SNP resulted protective towards pericarditis." (PMID 25369137, 2014).
pilocytic astrocytoma (1 paper, 2025). Pilocytic astrocytoma is a rare subtype of low-grade glioma of the central nervous system characterized by a well circumscribed, often cystic, brain tumor with a discrete mural nodule and long, hair-like projections that extend from the neoplastic astrocytes. "A case of a nonresectable pilocytic astrocytoma harboring a novel autophagy related 16 like 1-neurotrophic receptor tyrosine kinase 2 fusion is reported." (PMID 39326005, 2025).
preeclampsia (1 paper, 2025). Preeclampsia is a hypertensive disorder of pregnancy that is characterized by new-onset hypertension with proteinuria presenting after 20 weeks of gestation, and depending on mild or severe forms may initially present with severe headache, visual disturbances, and hyperreflexia. "It’s worth noting that even after adjustment for variables including maternal age, BMI and delivery mode, the expression of ATG16L1 remained significantly positively associated with preeclampsia." (PMID 41220585, 2025). "For ATG16L1, higher methylation at cg19193136 was unexpectedly associated with both higher gene expression and increased odds of preeclampsia." (PMID 41220585, 2025). "Pleiotropy was observed in the association between NSUN2, ATG16L1 and preeclampsia in the replication dataset as suggested by MR-Egger analysis." (PMID 41220585, 2025). "Higher genetically predicted ATG16L1 expression, a key autophagy gene, was linked to increased odds of preeclampsia." (PMID 41220585, 2025). "After outliers removal, the expressions of ATG16L1, PMVK and NSUN2 were found to be associated with odds of preeclampsia via the IVW method." (PMID 41220585, 2025). "Ultimately, functional studies in relevant cell and animal models are essential to confirm the causal impact of ATG16L1, PMVK, MAP3K14, NSUN2, and CDC25A on senescence phenotypes and preeclampsia pathogenesis." (PMID 41220585, 2025). "Higher predicted expression of 12 genes (including ATG16L1, BECN1, EP300, SGK1) was associated with increased odds of preeclampsia, while higher predicted expression of 17 genes was associated with decreased risk." (PMID 41220585, 2025). "Our findings implicate several genes operating through diverse pathways—including ATG16L1, MAP3K14, PMVK, CDC25A, and NSUN2—as potential mediators linking senescence processes to odds of preeclampsia." (PMID 41220585, 2025). "The results revealed that the expressions of ATG16L1, NSUN2 and PMVK were significantly downregulated in placental tissues from preeclampsia patients, whereas other key genes such as CDC25A and MAP3K14 did not vary significantly between groups." (PMID 41220585, 2025). "In conclusion, this multi-omics MR study, combined with preliminary experimental insights, pinpoints ATG16L1, PMVK, MAP3K14, NSUN2, and CDC25A as key candidate genes potentially mediating the link between cellular senescence pathways and odds of preeclampsia." (PMID 41220585, 2025). "Placental RT-PCR showed upregulated ATG16L1 and downregulated PMVK, MAP3K14, NSUN2, and CDC25A in preeclampsia." (PMID 41220585, 2025). "Key genes (ATG16L1, PMVK, MAP3K14, NSUN2, CDC25A) link cellular senescence to preeclampsia, offering insights for mechanistic studies and therapeutic targeting." (PMID 41220585, 2025). "These preliminary experimental findings lend support to the potential relevance of ATG16L1, PMVK, MAP3K14, NSUN2, and CDC25A dysregulation in preeclampsia pathophysiology." (PMID 41220585, 2025). "Synthesizing these results, dysregulation across interconnected pathways—autophagy (ATG16L1), inflammation (MAP3K14), metabolism (PMVK), cell cycle (CDC25A), and RNA methylation (NSUN2)—appears to converge on promoting placental cellular senescence, contributing to preeclampsia pathophysiology." (PMID 41220585, 2025).
respiratory infections (1 paper, 2021). "It will be valuable to assess whether human allelic variants of ATG16L1 confer altered resistance/susceptibility to respiratory infections such as IAV and whether drug‐based manipulation of non‐canonical autophagy can increase resistance at the respiratory epithelial barrier." (PMID 33586810, 2021).
sarcoidosis (1 paper, 2016). Sarcoidosis is a multisystemic disorder of unknown cause characterized by the formation of immune granulomas in involved organs. "We therefore tested genetic variants known to be strongly associated with an increased risk of CD (NOD2, IRGM, IL23R, and ATG16L1), sarcoidosis (BTNL2), and atopy (FLG) for association with OFG." (PMID 27306066, 2016). "DNA samples from 201 patients (111 OFG only and 90 OFG+CD) were genotyped for variants known to be strongly associated with an increased risk of CD (NOD2, IRGM, IL23R, and ATG16L1), sarcoidosis (BTNL2), and atopy (FLG)." (PMID 27306066, 2016). "We genotyped 201 patients and 1023 healthy controls for risk variants in NOD2, IRGM, IL23R, ATG16L1 (CD), BTNL2 (sarcoidosis), and FLG (atopy)." (PMID 27306066, 2016).
seminoma (1 paper, 2018). A radiosensitive malignant germ cell tumor found in the testis (especially undescended), and extragonadal sites (anterior mediastinum and pineal gland). "ATG1 and ATG16L1 are even further reduced in seminoma (SM) compared to non-seminoma (NSM)." (PMID 30245976, 2018).
small intestinal tumors (1 paper, 2025). "More importantly, we noted that aged Atg16l1/Xbp1/Rnaseh2bΔIEC mice spontaneously presented with nearly complete penetrance of small intestinal tumors (95.0%), when compared to Xbp1/Rnaseh2bΔIEC mice (61.7%)." (PMID 41057521, 2025).
squamous cell carcinoma (1 paper, 2023). A carcinoma arising from squamous epithelial cells. "For example, it has been reported that overexpression of the ATG16L1 gene occurs in patients with squamous cell carcinoma." (PMID 38136993, 2023).
temporal lobe epilepsy (1 paper, 2021). A localization-related (focal) form of epilepsy characterized by recurrent seizures that arise from foci within the temporal lobe, most commonly from its mesial aspect. "This study aimed to explore whether microRNA (miR) 223 affects microglial autophagy by targeting autophagy-related 16-like 1 (ATG16L1) in the kainic acid (KA) model of temporal lobe epilepsy (TLE)." (PMID 34381417, 2021).
ulcer (1 paper, 2016). "In what regards susceptibility to the ulcerative form of BU disease, the rs2241880 (T300A) SNP in the ATG16L1 gene was found to significantly protect patients from presenting the ulcer phenotype when a recessive genetic model was applied [OR, 0.35 (95% CI, 0.13–0.90); P = 0.02]." (PMID 27128681, 2016).
vasculitis (1 paper, 2021). "Specific deletion of Atg16l1 in smooth muscle cells increases the severity of LCWE-induced KD vasculitis." (PMID 34403365, 2021).